MIF (macrophage migration inhibitory factor)
Diseases named in the same sentence as MIF in open-access papers (continued):
Sharing a sentence is not in itself a finding about the gene and the disease.
liver fibrosis (continued). "Importantly, this study also showed that this MIF treatment directly suppressed activation of hepatic stellate cells, the main producers of scar tissue in liver fibrosis, through a CD74-driven pathway." (PMID 35091838, 2022). "Furthermore, TAM acceptance by liver resident macrophages induces an inflammatory response, and high levels of MIF in the exocytotic body, mediated by ITGαVβ5, can induce upregulation of liver fibrosis-related factors and proinflammatory genes." (PMID 35033111, 2022). "However, while some studies clearly show that MIF contributes to acute liver injury with effects on inflammation and hepatocyte apoptosis in ethanol-induced models of liver injury, other studies support a hepato-protective role of MIF in liver fibrosis." (PMID 35091838, 2022). "These cells could also decelerate liver fibrosis by secreting macrophage migration inhibitory factor (MIF) and may regenerate the liver by attenuating acute rejection and reducing inflammatory responses." (PMID 34805412, 2021). "In contrast to the hepatoprotective role that this cytokine exhibits in hepatotoxin-induced liver fibrosis and high fat diet-induced fatty liver degeneration, the current study unexpectedly demonstrated a clear-cut pro-fibrogenic effect of MIF in the MCD model of NASH." (PMID 33525493, 2021). "We therefore argue that increased MIF serum levels due to higher transcriptional activity may explain the attenuated liver fibrosis in patients with C/C or CATT 7/X, 8/X genotypes." (PMID 31370326, 2019). "However, individual chemokine concentrations, such as CCL3, CCL7, CCL24 (eotaxin-2), Macrophage Migration Inhibitory Factor (MIF), and soluble TNF-α receptor 1, were positively associated with Schistosoma-related liver fibrosis." (PMID 30619332, 2018). "Circulating soluble CD74 with MIF neutralizing activity was increased in primary biliary cirrhosis and was hypothesized to contribute to liver fibrosis." (PMID 26441987, 2015). "In chemically-induced liver fibrosis, it seems that MIF may have protective effects, possibly through an effect on the resolution of fibrosis." (PMID 26124760, 2015). "But, they do support the protective effects of MIF on hepatic fibrosis observed earlier in mice." (PMID 24551192, 2014). "A protective role has been ascribed to MIF in murine models of hepatic fibrosis." (PMID 24551192, 2014). "Furthermore, VA ameliorates liver fibrosis via the MIF/CD74 pathway stimulation." (PMID 40722864, 2025). "This disease-specific role of MIF in patients with AH is consistent with data from murine models, where MIF contributes to ethanol-induced liver injury but may protect from high-fat diet–induced liver injury and chemically induced liver fibrosis." (PMID 33945507, 2021). "Our results showed that MIF was important for the synthesis of the proinflammatory cytokines IL-6 and TNF in the myocardium in a model of TAA-induced liver fibrosis." (PMID 41020850, 2025). "The present study aims to investigate the role of betaine in the modulation of MIF-mediated oxidative stress, inflammation, and fibrogenesis in heart during TAA-induced liver fibrosis in mice." (PMID 41020850, 2025). "Considering the importance of antioxidants in the preventive and therapeutic strategy of chronic diseases, this study also investigates the modulating effect of betaine on myocardial MIF-mediated oxidative stress and inflammation in TAA-induced liver fibrosis." (PMID 41020850, 2025). "This study investigates the role of MIF in liver fibrosis and the modulating effect of betaine on MIF in thioacetamide (TAA)-induced liver fibrosis." (PMID 38927544, 2024). "Although further in vivo validation of these observations is required, our results indicate a possible strategy for the therapeutic use of MIF and TGF-β signaling inhibitors in patients with HIV-induced liver fibrosis." (PMID 24551192, 2014).
liver fibrosis (continued). "Our results suggest that MIF contributes significantly to lipid peroxidation of cardiomyocytes, as well as oxidative and nitrosative stress in myocardial tissue in mice with TAA-induced liver fibrosis compared to the control group." (PMID 41020850, 2025). "Notably, betaine attenuated MIF effects in myocardial tissue reducing levels of MDA, AOPP, TNF, TGF-β1, PDGF-BB and increasing SOD and catalase activity in the coexistence of liver fibrosis." (PMID 41020850, 2025). "Therefore, the aim of our study is to investigate the role of MIF in oxidative stress and inflammation in the myocardium during TAA-induced liver fibrosis." (PMID 41020850, 2025). "Macrophages may contribute to fibrosis by producing large amounts of the profibrotic cytokines MIF and ECM1 to promote liver fibrosis in the CE lesion microenvironment." (PMID 36569953, 2022). "MIF is a known regulator of chemokine expression following ethanol feeding with or without binge or chemically induced liver fibrosis by carbon tetrachloride, and in other cell types including endothelial cells, macrophages, and hepatocytes." (PMID 33945507, 2021). "Subsequently, they found that KCs engulfed PDAC‐derived exosomes carrying macrophage migration inhibitory factor (MIF) and could induce liver fibrosis pathways, especially transforming growth factor (TGF)‐β signalling, resulting in HSCs activation and fibronectin production." (PMID 36941028, 2023). "In this study, hepatic fibrosis (assessed histologically and by hydroxyproline measurement) was increased in absence of MIF in both CCl4- and TAA-induced liver fibrosis." (PMID 26124760, 2015).
parasitic infections (26 papers, 2007 to 2026). "Macrophage migration inhibitory factor (MIF) plays a distinct role in parasite infection-associated anemia." (PMID 40980010, 2025). "In T. gondii infection, our findings reported that the parasitic infection caused an augmentation of IL-6 and MIF levels." (PMID 39998112, 2025). "Additionally, the presence of macrophage migration inhibitory factor (MIF) in malaria infections has been linked to modulating monocyte recruitment and activation, impacting parasitemia levels in mice." (PMID 41171200, 2025). "In this research, MIF-deficient mice showed lower parasitemia and delayed host mortality." (PMID 38275363, 2023). "Interestingly P. falciparum produces a MIF homolog which can bind the MIF receptor CD7460 and circulating levels of this Plasmodium-derived MIF (pMIF) are associated with parasitemia and a greater proinflammatory state in the host." (PMID 29884801, 2018). "This review provides an overview of the complex involvement of MIF and D-DT in bacterial, viral, fungal, and parasitic infections." (PMID 38275363, 2023). "Several studies have shown that human macrophage migration inhibitory factor (MIF), a pleiotropic proinflammatory factor, is closely related to the occurrence and development of various parasitic diseases." (PMID 36033889, 2022). "Next to parasitic infections, MIF also plays a role in the modulation of the mammalian host microenvironment during other infections, such as bacterial infection." (PMID 35464430, 2022). "The present literature survey documents extensively the opposite activities of the polarising cytokines MIF and IL-10 during infections with various extracellular and intracellular pathogens, but with a special emphasis on parasitic disease." (PMID 35464430, 2022). "In parasitic infection, MIF is essential in activation of polymorphonuclear cells (PMN), such as neutrophils and eosinophils, and alternatively activated macrophages (AAM)." (PMID 34662363, 2021). "Macrophage migration inhibitory factor (MIF) is an important mediator for controlling parasitic infections such as T. gondii." (PMID 25926937, 2015). "MIF is a pluripotent immune factor known to regulate both innate and adaptive immune responses to bacterial and parasitic infections." (PMID 23272137, 2012). "The discovery in B. glabrata of a potential cytokine-like molecule displaying significant sequence similarity to MIF, raised the question of its potential involvement in the regulation of the snail immune response to parasite infection." (PMID 20886098, 2010). "Moreover, MIF is also involved in the protection of several parasitic infections, such as Taenia crassiceps and Toxoplasma gondii." (PMID 41171200, 2025). "For instance, during parasitic infections such as African trypanosomes, a persistent induction of GC’s may further fuel MIF production thereby undermining the beneficial anti-inflammatory activities of GC's and promoting GC resistance." (PMID 35464430, 2022). "Moreover, MIF is also involved in the protection of several parasitic infections, such as Taenia crassiceps, Toxoplasma gondii, and Trypanosoma cruzi." (PMID 36093199, 2022). "Taken together and despite the increase in IL-6 and MIF production by BeWo cells during parasite infection and under some oleoresin treatment conditions, in general, we observed that the oleoresin induced an anti-inflammatory profile to control parasite infection." (PMID 32938966, 2020). "We then tested resistance of MIF−/− mice to parasite infection in two models of acquired immunity." (PMID 31708913, 2019). "Human MIF has been reported to be secreted during parasitic infection." (PMID 29946046, 2018). "However, MIF remained upregulated when enrofloxacin was added to the villi, proving once again the importance of this cytokine in the reduction of the parasite infection." (PMID 28798905, 2017).
parasitic infections (continued). "Enrichment analysis showed that in the healthy mucosa, TSO influenced the expression of genes known to be associated with parasitic infections such as TCR signalling, phagocytosis, innate inflammatory response and macrophage migration inhibitory factor (MIF) signalling." (PMID 29184071, 2017). "As for other cytokines that play a dual role during the course of infection, MIF may be additionally involved in the pathophysiology of parasitic diseases." (PMID 23451183, 2013). "Thus, for the years to come, several aspects of the biology of MIF and its participation in the response to infectious diseases, including parasitic diseases, need to be addressed opening up new highways of research and, possibly, novel therapeutic strategies." (PMID 22496958, 2012). "After 24 h of parasite infection, murine J774 cells produced detectable amounts of TNF-α (34±5 pg/ml) that were strikingly raised (640±35 pg/ml, P<0.001) by adding recombinant mouse MIF (1 μg/ml)." (PMID 23451183, 2013). "The anti-MIF Nb treatment did not affect parasitemia development in TgAlbCre-IL10-/- mice, but it clearly prevented anemia from further progressing." (PMID 32012211, 2020). "Similar to Mif−/− mice, anti-MIF IgG treatment did not affect parasitemia development but increased the median survival time compared to control antibody treated mice, suggesting a role for extracellular MIF in disease pathogenesis." (PMID 25255103, 2014).
Alzheimer disease (25 papers, 2013 to 2025). A progressive, neurodegenerative disease characterized by loss of function and death of nerve cells in several areas of the brain leading to loss of cognitive function such as memory and language. "Experimental studies showed that MIF deficient mice had reduced astrocyte activation and tau hyperphosphorylation in Alzheimer’s disease models." (PMID 33407905, 2021). "In patients with clinical pre-dementia disease stage, MIF has been associated with biomarkers of Alzheimer’s disease pathology and predicted cognitive impairment." (PMID 33407905, 2021). "MIF also has been associated with the development of cognitive impairment, mainly in Alzheimer’s disease." (PMID 33407905, 2021). "CD74 is a high affinity receptor for MIF (macrophage migration inhibitory factor) on APCs and implicated in a number of inflammatory processes in neurodegenerative affections such as Alzheimer’s disease." (PMID 33042148, 2020). "This hypothesis is strengthened by studies showing increased MIF production is associated with Alzheimer disease and mild cognitive impairment suggesting that MIF is involved in the neuro-inflammatory process occurring in cognitive decline." (PMID 33407905, 2021). "The macrophage migration inhibitory factor (MIF) pathway has a pivotal relationship in shaping the immunological microenvironment in Alzheimer’s disease." (PMID 40560886, 2025). "The lead compound, as well as conformation-sensitive antibodies, specifically interacts with an oxidized conformer of MIF (oxMIF) enriched in postmortem brain homogenates of patients with Alzheimer's disease (AD)." (PMID 41418773, 2025). "MIF is expressed by both neurons and glia and is elevated in CSF from individuals with Alzheimer disease." (PMID 36721240, 2023). "One study has shown MIF can bind to the amyloid protein, possibly leading to accumulation of amyloid-beta in Alzheimer disease." (PMID 33407905, 2021). "Aberrant expression of MIF has shown to result in several pathological diseases of the CNS including Alzheimer’s disease, autism spectrum disorders, encephalomyelitis, and tumorigenesis." (PMID 30180853, 2018). "An upregulation of MIF has been reported to be detrimental in several neurodegenerative diseases such as Alzheimer’s disease (AD), mild cognitive impairment, Parkinson ́s disease and multiple sclerosis (MS)." (PMID 28726057, 2017). "The protein assembly modulator active in the Alzheimer’s Disease mouse, targets MIF." (PMID 40977882, 2024). "Neuronal secretion of MIF might serve as a defense mechanism to compensate for decreased cognitive function in Alzheimer's disease, and increased MIF level could be a potential biomarker for the disease." (PMID 32964038, 2020). "MIF is also found to be elevated in numerous neuroinflammatory and neurodegenerative diseases, including: Multiple sclerosis, meningitis, encephalitis tick-borne borreliosis, subarachnoid hemorrhage, and Alzheimer’s disease." (PMID 31906137, 2019). "On the other hand, in-vitro, in-vivo, and ex-vivo preclinical data, as well as data from Alzheimer' s disease patients have shown that MIF is increased during the course of the disease and that therapeutic targeting of MIF could beneficial effects on the Alzheimer' s disease course." (PMID 33319101, 2020). "In neurodegenerative conditions, such as Alzheimer’s disease (AD), Parkinson’s disease (PD), and amyotrophic lateral sclerosis (ALS), MIF plays a dichotomic role." (PMID 34445510, 2021). "Hence, we propose DRhQ as an effective therapeutic with possible clinical applications for patients with MS as well as those with other MIF/CD74 driven CNS conditions, including ischemic injury, traumatic brain injury, methamphetamine use disorder and Alzheimer’s disease." (PMID 37933270, 2023).
Arthritis (25 papers, 2006 to 2024). Inflammation of a joint. "During RRV infection, MIF plays an important role in RRV-induced arthritis and causes severe inflammation and tissue damage." (PMID 31632367, 2019). "Arthrogenic alphaviruses can cause debilitating illnesses characterized by arthritis and arthralgia, and evidence suggests that both MIF and CD74 play a critical role in mediating alphaviral disease." (PMID 30976033, 2019). "Arthritis and cancer, two conditions previously associated with MIF and the -173 GC SNP, presented significant associations in at least one model, while IBD did not demonstrate any association." (PMID 29545822, 2018). "Single nucleotide polymorphism (SNP) -173 G/C (rs755622) on MIF gene has been associated with numerous diseases, such as arthritis and cancer." (PMID 29545822, 2018). "MIF is implicated in animal models of inflammatory diseases, including arthritis, glomerulonephritis, acute lung injury and sepsis (for recent review)." (PMID 19066630, 2008). "To elucidate the role of MIF in MMP-2 production, we produced zymosan-induced arthritis (ZIA) in MIF gene-deficient and wild-type mice." (PMID 16872482, 2006). "To evaluate the in-vivo role of MIF in MMP-2 production, we induced acute arthritis by intra-articular injection of zymosan in MIF gene-deficient and wild-type mice." (PMID 16872482, 2006). "Moreover, MIF gene-deficient mice exhibit significantly less synovial inflammation than wild-type mice after arthritis induction with type II collagen." (PMID 16872482, 2006). "Elevated levels of MIF family proteins are implicated in inflammatory diseases such as asthma, acute respiratory distress syndrome, and arthritis, while antibody neutralization of MIF proteins attenuates inflammatory symptoms in animal models." (PMID 37080391, 2023). "Studies in animal models demonstrate that blocking MIF induces a protective effect against inflammation in adjuvant-induced arthritis." (PMID 33133605, 2020). "In summary, stimulation with TNFα, IL‐6 and MIF lead to cytokine-mediated cartilage degradation, a key feature of arthritis." (PMID 33374446, 2020). "It was also shown in vitro that MIF facilitated RANKL-induced osteoclastogenesis, which suggests that MIF contributes directly to bone erosion as well as to inflammation in arthritis." (PMID 27313578, 2016). "In monocyte-derived dendritic cells (DC) from RA patients, TLRs significantly enhance production of proinflammatory mediators, including MIF, thereby amplifying the proinflammatory loop seen in arthritis." (PMID 22046508, 2010). "In type II collagen-induced arthritis, a murine model of RA, treatment with neutralizing anti-MIF antibodies delays the onset, and decreases the frequency, of arthritis." (PMID 16872482, 2006). "Previously, we reported the important role of MIF in angiogenesis, and the contribution of MIF to arthritis was also shown by independent studies." (PMID 16872482, 2006). "In addition, MIF inhibitors have shown potent anti-inflammatory activity in macrophages and arthritis models." (PMID 39845946, 2024). "Moreover, in arthritis, myelitis, EAE, and mouse autoimmune models, MIF deficiency was associated with reduced pathologies and in some of these models a reduction in T cell activation was observed." (PMID 37946732, 2023). "Similarly, blockade or depletion of MIF reduces leukocyte accumulation in models of infection/endotoxemia, arthritis and atherogenesis." (PMID 22046508, 2010). "We found significantly elevated MMP-2 protein levels in knee homogenates of wild-type mice compared with MIF gene-deficient mice (wild-type, 1.3 ± 0.08 ng/mg of protein and MIF gene-deficient, 0.82 ± 0.08 ng/mg of protein; P < 0.05), pointing to an important role of MMP-2 in arthritis." (PMID 16872482, 2006).